BRAF (B-Raf proto-oncogene, serine/threonine kinase)
Diseases named in the same sentence as BRAF in open-access papers (continued):
Sharing a sentence is not in itself a finding about the gene and the disease.
melanoma (continued). "Melanomas are a heterogeneous group of tumors characterized by specific genetic alterations, including mutations in kinase, such as BRAF or c-kit." (PMID 23738077, 2013). "In BRAF V600E-mutated melanomas, after an initial robust response, there is disease progression within a median of 5–7 months." (PMID 23717811, 2013). "Melanomas carrying a BRAF mutation constitutively activate the mitogen-activated protein kinase (MAPK) pathway, promoting cellular proliferation and preventing apoptosis." (PMID 23420786, 2013). "For example, in the context of melanoma, cancers with the BRAF(V600E) mutation can be treated with vemurafenib (Zelboraf, Plexxikon) resulting in outstanding response." (PMID 23587292, 2013). "Following tumor enrichment by macro-dissection of an area containing approximately 85% melanoma nuclei, molecular testing demonstrated the presence of a 1799T>A (V600E) mutation in BRAF." (PMID 24220097, 2013). "Further, BRAF mRNA has been found subject to alternative splicing, with different transcript variants identified in colorectal cancer as well as in melanoma." (PMID 23673558, 2013). "Dabrafenib has demonstrated antitumor activity in several BRAF-mutated malignancies including melanoma, colorectal carcinoma, papillary thyroid carcinoma, NSCLC, and ovarian carcinoma." (PMID 23470635, 2013). "According to the prevailing multistep model of melanoma development, oncogenic BRAF or NRAS mutations are crucial initial events in melanoma development." (PMID 23861977, 2013). "Approximately half of melanomas harbor a somatic point mutation of the BRAF oncogene at codon 600 (V600E and V600K)." (PMID 24194739, 2013). "An activating BRAF mutation is detected in 40% of melanomas, the most common being BRAF V600 E mutation." (PMID 23516541, 2013). "Novel therapies targeting the BRAF oncogene, which is mutated in almost 50% of all melanomas, have demonstrated clinical benefit in melanoma patients." (PMID 23527225, 2013). "Recently, an innovative approach based on inhibitors of the mutated BRAF gene (which represents the most prevalent alteration in melanoma patients) appears very promising from the clinical point of view." (PMID 23317446, 2013). "In summary, we have presented a comparison study of three different methods for the detection of V600E mutations in the BRAF gene in FFPE specimens of malignant melanoma." (PMID 23326492, 2013). "Although many advanced melanoma present with a mutation in BRAF, this BRAF-V600E mutation, although contributing to Erk1,2 phosphorylation, is not sufficient for sustained activation." (PMID 24069584, 2013). "The aim of this study was to evaluate the predictive and prognostic impact of genetic disturbances and expression levels of BRAF together with NRAS mutations in patients treated with DTIC monotherapy for advanced melanomas." (PMID 23673558, 2013). "The most promising results in patients with BRAFmut melanoma have been seen with drugs designed to selectively target the mutated and activated form of the BRAF kinase." (PMID 23340652, 2013). "Other BRAF mutations include V600K and V600D/R, accounting for 16–29% and 3% of all BRAF mutations in melanoma, respectively." (PMID 24298448, 2013). "Mutations in BRAF gene were detected in 223/451 (49%) primary melanomas and 153/298 (51%) metastatic tissues, whereas NRAS mutations were found in 46/312 (15%) primary tumors and 34/216 (16%) melanoma metastases." (PMID 23987572, 2013). "Despite this, the most common somatic mutation found in melanoma, BRAF V600E (A>T), can be targeted with new therapies, but is not a UV fingerprint (C>T) mutation." (PMID 23303275, 2013). "In 2011, two new agents were approved for the treatment of patients with advanced melanoma; ipilimumab, a novel immunotherapy, and vemurafenib, a specific BRAF inhibitor for patients with BRAFV600-mutation positive melanoma." (PMID 24423086, 2013).
melanoma (continued). "The two substitutions (V600E and V600K) represent 95% of all BRAF mutations in melanoma, and both create a constitutively active kinase that is independent of receptor tyrosine kinase or RAS." (PMID 23476798, 2013). "Molecular studies demonstrated that the melanoma was positive for the 1799T>A (V600E) mutation in the BRAF gene." (PMID 24220097, 2013). "Trametinib is an inhibitor of this pathway, and has been shown to have an effect on BRAF mutated melanoma." (PMID 24499550, 2013). "The MAPK/Extracellular signal-regulated kinase (ERK) signaling pathway is commonly activated in melanoma by mutations in BRAF (in 50% of melanomas), NRAS (10–20%), and less frequently in MEK1 and MEK2 (∼8%)." (PMID 23515890, 2013). "In August 2011, an alternative melanoma regimen, for patients positive for BRAF mutations, was brought into the market with the FDA approval of Vemurafenib (Zelboraf, Plexxikon/Roche)." (PMID 23634303, 2013). "Activating mutations of the BRAF oncogene have been reported in 33% to 47% of primary melanomas and 41% to 55% of MM." (PMID 23976959, 2013). "In this sense, molecular heterogeneity as well as polyclonality of BRAF mutations in primary melanomas have been widely reported." (PMID 23987572, 2013). "A broad range of human tumors have been found to contain BRAF mutations, including approximately 50% of melanomas." (PMID 23603840, 2013). "New Zealand has a high incidence of melanoma and it was therefore of interest to compare the frequencies of activating BRAF and NRAS mutations in New Zealand-derived melanoma lines with published values." (PMID 23658559, 2013). "Past studies have shown that histone deacetylase (HDAC) and mutant BRAF (v-Raf murine sarcoma viral oncogene homolog B1) inhibitors synergistically kill melanoma cells with activating mutations in BRAF." (PMID 23744355, 2013). "Activating BRAF mutations have also been documented in a variety of human cancers other than melanoma, such as ∼10% in colorectal cancer (CRC), approximately 50% in thyroid cancer, and several percent in NSCLC." (PMID 23991070, 2013). "One of the most interesting targets is analysis of the BRAF gene, mutated in 50–70% of melanomas, and furthermore associated with exposure to ultraviolet light." (PMID 23476798, 2013). "For the 294 cell lines (GSK set) for which genomic information was available, we computed the occurrence of each mutation-lineage pair; there were 2132 such pairs (e.g. BRAF::Melanoma)." (PMID 23577104, 2013). "Following the recent approvals by both the Food and Drug Administration and the European Medicines Agency, vemurafenib is now increasingly used for treatment of patients with late-stage melanoma harboring BRAF(V600E/K) mutations." (PMID 24023633, 2013). "BRAF mutations occur in approximately 8% of all human cancers, with high mutation frequency in malignant melanoma (50-70%), classic papillary carcinoma of the thyroid (40-70%), colorectal cancer (CRC, 5-15%), ovarian cancer and hairy cell leukemia (5-100%)." (PMID 24252159, 2013). "Vemurafenib (PLX4032), a BRAF selective kinase inhibitor and sorafenib, a multi-target inhibitor, find application in selected BRAF-mutation positive melanomas." (PMID 24267151, 2013). "While a recent report suggests that autophagy was less when BRAF was mutated in melanoma, at the time points that we examined there was significant autophagic flux in melanoma cell lines with mutations in BRAF." (PMID 23383069, 2013). "BRAF mutated melanomas are more common on the trunk and limbs compared to head and neck tumours and this again was thought to be due to differences in sun exposure but this has not been proven as yet." (PMID 23796690, 2013). "Frequent somatic mutational activation of BRAF has been observed in human cancers, including melanomas, gliomas, colorectal cancers, lung cancers and others." (PMID 24252190, 2013).
melanoma (continued). "Examples include single nucleotide variants (SNVs) involving codons V600 and L597 in the gene BRAF in melanomas, which are associated with sensitivity to BRAF and MEK inhibitors, respectively." (PMID 24112718, 2013). "For example, the BRAF inhibitor sorafenib is inactive against malignant melanoma with BRAF V600E mutations, while another BRAF inhibitor, vemurafenib, is highly active." (PMID 23587187, 2013). "In our work, we used cutaneous melanoma cell lines where BRAF mutations are the most common alteration and BRAF is considered an oncogene." (PMID 23904987, 2013). "The presence of BRAF mutation was also analyzed according to the histological subtype of primary melanoma." (PMID 23976959, 2013). "BRAF somatic mutations are also very common in naevi and melanoma and this led recently to the first therapy ever conferring an increased survival in melanoma." (PMID 23796690, 2013). "Colombino and colleagues found 6 of 44 BRAF mutant primary melanoma patients whose primary melanomas were positive for the BRAF V600E mutation, yet had a BRAF wild-type secondary lesion." (PMID 23951556, 2013). "Studies revealed that regulation of the Ras-Raf-MAPK pathway is abrogated in the majority of melanoma tumors as a result of activating NRAS or BRAF mutations, which are mutually exclusive and present in up to 90% of cutaneous melanomas." (PMID 23555633, 2013). "Melanomas are characterized by mutation in NRAS (20% of tumors), and BRAF in about 50% of cases, and are different subpopulations in melanomas cases." (PMID 23984088, 2013). "Approximately 40%–60% of patients diagnosed with malignant melanoma will have a mutation in the gene coding for the BRAF protein, most commonly a valine to glutamic acid substitution in the 600 position of the protein (V600E)." (PMID 24455677, 2013). "BRAF V600E mutation is most prominent in melanoma (40–60%), papillary thyroid carcinoma (45%), low grade serous ovarian carcinoma (35%), and in colorectal adenocarcinoma (5–15%)." (PMID 24298448, 2013). "miR-193a was found to function as a tumor suppressor in several cancer types and is under expressed in melanomas containing a BRAF mutation." (PMID 24047116, 2013). "Recently, NRAS/BRAF activation was shown to mediate an epithelial-to-mesenchymal transition (EMT) switch in late-stage melanoma that relies on TWIST1; ZEB1, and E-cadherin loss and results in enhanced invasion." (PMID 24416617, 2013). "BRAF mutation rate varies among different types of tumors, predominantly in malignant melanoma, thyroid papillary cancer, and sporadic CRC." (PMID 23637996, 2013). "We treated melanoma cell lines displaying different BRAF and GNAQ mutational status with the mTOR inhibitor RAD001 and with the MEK1/2 inhibitor U0126 and evaluated the effects in the growth of the cell lines and in mTOR and MAPK pathway effectors expression." (PMID 23904987, 2013). "Among these, BRAF has been shown to play a key role through activating mutations in malignant melanomas." (PMID 23673558, 2013). "The oncogene BRAF (v-raf murine sarcoma viral oncogene homolog B1) is frequently mutated in melanoma (40–50% of cases) and has resulted in the development of BRAF-targeting kinase inhibitors, like vemurafenib (PLX4032) and dabrafenib." (PMID 24023633, 2013). "Overall, mutations were detected in 49% primary melanomas and 51% metastases, for BRAF gene, and 15% primary tumors and 16% secondaries, for NRAS gene." (PMID 23987572, 2013). "Overall, BRAF or NRAS mutations were observed in 376/749 (50%) or 80/528 (15%) melanoma tissue samples, respectively." (PMID 23987572, 2013). "In contrast to others reporting the BRAF V600K mutation to occur in about 6–20 % of BRAF-mutated melanomas, we only observed this mutation in one out of 30 metastases (3.3 %)." (PMID 23673558, 2013). "The NRAS and BRAF genes are frequently mutated in melanoma, suggesting that the NRAS-BRAF-MEK-ERK signaling pathway is an important target for therapy." (PMID 23658559, 2013).
melanoma (continued). "In 2002, oncogenic mutations in the serine/threonine kinase BRAF was identified in nearly 70% of cutaneous melanomas, a percentage closer to 50% when considering a higher number of melanoma specimens." (PMID 24416617, 2013). "A marked citotoxicity was observed in differentated melanoma cells regardless BRAF mutational status." (PMID 24238212, 2013). "To gain a more profound understanding in the role of BRAF or NRAS mutations in the development of melanoma from nevi we compared the genotype and BRAFV600E protein expression of melanomas and their associated nevi with control nevi of the same patient." (PMID 23861977, 2013). "The most promising include antiangiogenic drugs, inhibitors of v-RAF murine sarcoma viral oncogene homolog B1 (BRAF) for BRAF V600E mutated melanoma, and inhibitors of the epithelial growth factor receptor for non-small cell lung cancer." (PMID 23340652, 2013). "A deeper understanding of the molecular pathogenesis of melanoma has revealed that in 40% to 60% of the cases, the BRAF mutation is present in the tumor cells." (PMID 24455362, 2013). "Highly sensitive methods of mutation testing are particularly important given the recently reported intra- and inter-tumor heterogeneity of BRAF V600E mutations in melanoma." (PMID 23326492, 2013). "Disease-free and overall survival is improved by treatment with the specific inhibitor vermurafenib, in patients with advanced or metastatic melanomas with BRAF mutations." (PMID 24119386, 2013). "The frequencies of oncogenic BRAF mutations were similar in the melanoma part (63.0%) and in the nevus part (65.2%) with a concordance of 80.4%." (PMID 23861977, 2013). "Melanomas on skin without chronic sun-induced damage had frequent mutations in BRAF, on the contrary acral and mucosal melanoma and melanoma on the skin with chronic sun damage frequently are characterized by Kit mutations." (PMID 23691346, 2013). "Mutations of BRAF were found in several tumors, such as malignant melanoma, colorectal cancer, and so on." (PMID 23637996, 2013). "Dabrafenib has also prolonged progression-free survival and overall survival when compared to dacarbazine in patients with BRAF V600E mutated melanoma in the BREAK3 trial." (PMID 23717811, 2013). "Overall, a total of 749 tumor samples (451 primary melanomas and 298 melanoma metastases) was screened for BRAF mutations; among them, available DNA from 528 specimens (312 primary melanomas and 216 melanoma metastases) was analyzed for mutations in NRAS gene." (PMID 23987572, 2013). "Recently, we have shown that the BRAF inhibitor dabrafenib (GSK2118436) is also active in several non-melanoma BRAF-mutated cancers." (PMID 23470635, 2013). "It shows high accuracy and precision of pyrosequencing in quantitative identification of BRAF mutations in melanoma cell lines as well as in FFPE tumors." (PMID 23555633, 2013). "Recently, Colombino and colleagues demonstrated that melanoma lesions in the brain have an increased incidence of mutations in the BRAF protein compared with systemic melanoma." (PMID 24455677, 2013). "For example, as a difference with melanoma patients, colon cancer patients harbouring the same BRAF(V600E) mutation show a very limited response to vemurafenib." (PMID 23587292, 2013). "At a molecular level it is believed that activation of the mitogen-activated protein kinase (MAPK) signaling pathway as a result of somatic mutations of NRAS or BRAF is a crucial event in this multistep development of melanoma." (PMID 23861977, 2013). "Consistently, activating mutations of BRAF and loss of functional p16INK4a and p14ARF were detected in the majority of melanomas." (PMID 24416617, 2013).
melanoma (continued). "Several inhibitor combinations effective for melanomas with activating RAS or BRAF mutations were recently discovered." (PMID 24000324, 2013). "In our experience, mutations in BRAF gene occur in 43% of primary melanomas and 48% of metastatic melanomas." (PMID 23317446, 2013). "The landscape of melanoma therapy has changed dramatically within the last few years with the discovery that the majority of melanomas harbor activating mutations in BRAF and that virtually all melanomas exhibit constitutive activity in the MAP kinase pathway." (PMID 23527225, 2013). "Treatment of the BRAF V600E-mutated melanoma cell line 1205Lu with dinaciclib (30 nM, 0–48 hrs) led to a decrease in the extent of RB phosphorylation at Ser 807/811." (PMID 23527225, 2013). "BRAF mutations occur in approximately 8% of all human cancers and approach 50% in melanoma and papillary carcinoma of thyroid." (PMID 24252159, 2013). "BRAF somatic mutations have been reported in 66% of malignant melanomas and are likely to be a crucial step in the initiation of melanocytic neoplasia, as they are found also in melanocytic nevi." (PMID 23209607, 2012). "So far our report is the first study on this issue which demonstrates the correlation between BRAF mutation and poor melanoma patient survival in a reliable statistical point of view." (PMID 23056577, 2012). "Although melanoma metastases have been found to contain thousands of mutations, the V600E BRAF mutation is clearly a driver of the neoplastic phenotype and is present in approximately 50% of melanomas." (PMID 22846499, 2012). "While BRAF mutations are significantly less frequent in these melanoma subtypes, activating mutations in the KIT gene are often seen." (PMID 22339359, 2012). "Considering the wide-spread activating mutations in BRAF this observation was somewhat surprising especially as MAPK signal attenuation by Spry2 was suggested to be lost in melanoma cells harboring BRAFV600E." (PMID 22535842, 2012). "Our data indicated a frequency of 48% for cerebral V600BRAF mutations, with a quite similar incidence rate of such BRAF variants among primary melanomas and corresponding brain metastases from the same patients." (PMID 22594466, 2012). "Targeting both MEK and mTOR is a method to target melanoma which often have mutations at BRAF and increased activation of the PI3K/PTEN/Akt/mTORC1 pathway." (PMID 23455493, 2012). "Approximately 50% of malignant melanomas harbor a BRAF activating mutation, the majority of these being BRAFV600E, which results in constitutive activation of BRAF and increased activation of the MAP kinase pathway." (PMID 22912849, 2012). "A need for a conclusive meta-analysis on the effect of BRAF mutation on melanoma patient survival has been emerged due to the controversial reports on this issue." (PMID 23056577, 2012). "The RAS/MAP kinase pathway has attracted attention because activating mutations of the BRAF serine/threonine kinase was described in over 50% of melanomas." (PMID 22433222, 2012). "Mutation of BRAF is a predominant event in cancers with poor prognosis such as melanoma and colorectal cancer." (PMID 23056577, 2012). "While BRAF mutations represent the most frequent oncogenic alteration in melanomas so far (BRAFV600E in up to 70% of cases), NRAS mutations occur in 15 to 30%." (PMID 22535842, 2012). "For example, sorafenib was designed as a potent nanomolar (nM) inhibitor of BRAF which a protein implicated in the survival of melanoma cells." (PMID 22815915, 2012). "Activating mutations in the gene encoding the serine-threonine protein kinase BRAF have been observed in 40–60% of melanomas, 40–70% of papillary or anaplastic thyroid cancers and 7–8% of all cancers." (PMID 25562798, 2012). "In melanoma, mutations in the BRAF oncogene are among the most commonly reported molecular alterations, and BRAF is currently an exciting therapeutic target." (PMID 22235286, 2012).